CD4 (CD4 molecule)
Diseases named in the same sentence as CD4 in open-access papers (continued):
Sharing a sentence is not in itself a finding about the gene and the disease.
triple-negative breast carcinoma (49 papers, 2013 to 2026). An invasive breast carcinoma which is negative for expression of estrogen receptor (ER), progesterone receptor (PR), and human epidermal growth factor receptor 2 (HER2). "A study of triple-negative breast cancer (TNBC) showed that a high CD4 + Tcm enrichment score was associated with worse RFS of patients with TNBC." (PMID 36185274, 2022). "Data from a study on triple negative breast cancer found a significant association of low CD4/CD8 ratio and impaired relapse-free and overall survival." (PMID 35326536, 2022). "The increased infiltration of CD4+ TILs was associated with better prognosis of patients with esophageal squamous cell carcinoma and triple-negative breast cancer." (PMID 34616731, 2021). "A significantly higher TI naive CD4+ T cell count was associated with other indicators of poor prognosis — triple-negative breast cancer subtype, lymphovascular invasion, LN metastasis and distant metastases." (PMID 28290464, 2017). "In triple-negative breast cancer, higher CD4/CD8 ratios and CD30 expression levels correlate with poor prognosis and lower OS rate." (PMID 38159260, 2024). "Prior research has highlighted the importance of a low CD4+/CD8+ TIL ratio as a favorable prognostic indicator in triple-negative breast cancer (TNBC)." (PMID 39769460, 2024). "The main reason for this was that the CD4+ T cells and CD8+ T cells (primary effector sTIL subtypes) had been linked to a better response to anti-tumor treatment in triple-negative breast cancer." (PMID 36874102, 2023). "The aim of this study is to investigate the gene expression module of tumor-infiltrating CD4+T cells and its potential roles in modulating immune cell functions in triple-negative breast cancer." (PMID 33301062, 2021). "Our findings of a low ratio of CD4+/CD8+ in mice injected with MB/virus complexes following US coupled with increased necrosis indicate a successful outcome of the MB/OV treatment that agrees with previous human studies of triple-negative breast cancer." (PMID 39769460, 2024). "Moreover, Teo and colleagues have shown, that the CDK4/6 inhibitor ribociclib does not impair activation and cytotoxic potential of tumor-infiltrating CD8+ and CD4+ T cells in a triple-negative breast cancer mouse model." (PMID 36817127, 2023). "We identified CD8+ve T cells, M2 macrophages, and neutrophils to be enriched in luminal A and T cells CD4+naïve, natural killer (NK) cells activated, T follicular helper (Tfh) cells, dendritic cells activated, and neutrophils in triple-negative breast cancer (TNBC) subtypes." (PMID 37810779, 2023). "xCell analysis reveals that plasma cells and CD4+ Tcm in the tumor microenvironment may play a role in the progression of triple-negative breast cancer, although only immune cells were investigated." (PMID 32728493, 2020). "L Deng suggested that plasma cells and CD4+ central memory T (Tcm) cells in the TME may play a role in the subsequent progression of triple-negative breast cancer." (PMID 32544083, 2020). "Recent analysis with xCell reveals that plasma cells and CD4+ Tcm in the tumor microenvironment may play a role in the progression of triple-negative breast cancer, although only immune cells were investigated." (PMID 32728493, 2020). "However, a recent publication, asscessing FOXP3 expression in triple negative breast cancers, documented improved survival in patients with high levels of tumour infiltrating CD4+CD25+FOXP3+Tregs." (PMID 23320561, 2013). "For instance, in triple-negative breast cancer (TNBC), patients with low expression of the CD247 and CD4 gene phenotypes tend to have poorer outcomes." (PMID 40710213, 2025). "The expression of SLC1A5 confers advantages in glutamine uptake in triple-negative breast cancer cells, accompanied by the attenuation of CD8+ and CD4+ T cell function." (PMID 39223142, 2024).
triple-negative breast carcinoma (continued). "In triple negative breast cancer, the deletion of RNF2 enhances the activation and infiltration of CD4 + -T and NK cells to promote anti-tumor immunity." (PMID 37037816, 2023). "A single dose of bevacizumab reduced the density of angiopoietin-2-positive vessels while improving the infiltration of CD4+ T and CD8+ T cells, and mature dendritic cells in patients with primary triple-negative breast cancer." (PMID 34188163, 2021). "We previously found that CD4+ and CD8+ TILs are correlated with a favorable prognosis in triple-negative breast cancer (TNBC)." (PMID 33726701, 2021). "In this study, we investigated CD20+ TILs in triple-negative breast cancer (TNBC) and their relationship with T lymphocyte subsets (CD4+, CD8+, CD25+, and FOXP3+), including their combined prognostic value using an immunohistochemical staining method." (PMID 33726701, 2021). "The objective of this systematic review and meta-analysis was to determine the prognostic value of total tumor-infiltrating lymphocytes (TILs) and subtypes of TILs (CD4+, CD8+, and FOXP3+) in triple-negative breast cancer (TNBC)." (PMID 32131780, 2020). "Above 5% CD4+CD25+proportion of T cells produced the HR to be 1.76 (95%CI 1.07, 2.87) In stage 0-II patients, and 3.59 (95%CI 1.05, 12.29) in triple negative breast cancer patients." (PMID 26462021, 2015). "Significantly, we found that systemic administrationof SLR-LNPs reprogrammed the breast TME to enhance the infiltrationof CD8+ and CD4+ T cells with antitumor function,resulting in enhanced response to αPD-1 ICI in an orthotopicEO771 model of triple-negative breast cancer." (PMID 38652829, 2024). "Furthermore, the CD4/CD8 ratio is in some cancer types, like the triple negative breast cancer, a useful prognostic tool, but can also be used as indicator to monitor the course of a therapy with immune checkpoint inhibitors." (PMID 36856809, 2023). "In triple-negative breast cancer, tumors with high levels of infiltrating CD8+ T cells and memory CD4+ T cells might result in a better prognosis; this is consistent with BLCA." (PMID 34589112, 2021). "Noteworthy, CD4/CD8 ratio < 1 at the tumor–host interface has prognostic value in triple-negative breast cancer; we likewise found the mean CD4/CD8 ratio to be at 0.47, which was less than 1 and negatively associated with PLIN3, indicating that patients with PLIN3high tumor had a poor outcome." (PMID 38554152, 2024). "In this study, we discover immunological markers, such as tumor-infiltrating lymphocytes, CD8+, CD4+, FoxP3+, CD20+ lymphocytes, and their PD1 positivity or negativity, with the ability to predict benefits from eribulin within locally advanced or metastatic triple-negative breast cancer." (PMID 35814376, 2022). "It was also associated with a higher number of both CD4+ and CD8+ TILs, an absence of lymphovascular invasion and increased formation of Tertiary Lymphoid Structures (TLS) with higher levels of IFN-γ, IL-2 and IL-12 mRNA (Th1 associated cytokines) in triple-negative breast cancer." (PMID 35008422, 2022). "In triple-negative breast cancer (TNBC), single marker-positive intratumoral TILs did not affect prognosis, however CD4/PDL1, CD8/PD1, and CD8/PDL1 double-positive TILs were significantly associated with TNBC recurrence (p<0.05, p<0.01, and p<0.001, respectively)." (PMID 36132149, 2022).
cutaneous leishmaniasis (48 papers, 2010 to 2025). Leishmaniasis affecting the skin. "Here, we demonstrate the association of CD4+ T cells with cytotoxic capacity in CL lesion environment, potentially implicating their contribution to the pathophysiology of cutaneous leishmaniasis." (PMID 39497830, 2024). "It is well established that CD4+ T cells play a pivotal role in the protective response during human cutaneous leishmaniasis caused by L. brasiliensis." (PMID 39497830, 2024). "Efficient vaccination against the parasite Leishmania major, the causative agent of human cutaneous leishmaniasis, requires development of type 1 T-helper (Th1) CD4+ T cell immunity." (PMID 23840706, 2013). "In animal models of cutaneous leishmaniasis caused by L. major, the immunological dogma correlates resistance to disease with the development of a CD4+ Th1 response, and susceptibility with a CD4+ Th2 response." (PMID 22919688, 2012). "Studies of Tregs in cutaneous leishmaniasis demonstrated the involvement of CD4+CD25+ Tregs in cutaneous leishmaniasis caused by L. major and L. amazonensis in mice and by L. braziliensis in humans." (PMID 22928057, 2012). "Collectively, our results provide the first evidence that senescent cytotoxic CD4+ T cells may play a significant role in the skin pathology associated with human cutaneous leishmaniasis." (PMID 39497830, 2024). "This study also showed that blockade of LIGHT with soluble receptors in mice infected with L. major, a cause of cutaneous leishmaniasis, resulted in reduced IL-12 generation, associated with diminished CD4+ T cell IFNγ production and increased parasite growth and disease." (PMID 21998581, 2011). "Using immunoproteomics approach, we identified that DLD63-79 peptide derived from Leishmania major DLD, an important metabolic enzyme in the parasite, as a strong inducer of CD4+ T cell response in a mouse model of experimental cutaneous leishmaniasis." (PMID 40096189, 2025). "Adoptive transfer studies have shown that IL-10 produced by the CD4+ CD25− Foxp3− T cells suppressed the healing response in cutaneous leishmaniasis." (PMID 40502169, 2025). "In this study, we demonstrate that the transcriptomic signatures of cytotoxic markers in the lesions of patients with cutaneous leishmaniasis correlate with CD4+ T cell signature genes." (PMID 39497830, 2024). "Overall, this study provides the first evidence that senescent cytotoxic CD4+ T cells contribute to mediating skin pathology in human cutaneous leishmaniasis through bystander cytolysis via NK receptors." (PMID 39497830, 2024). "While recent studies have shown that Leishmania-specific memory CD4+ T-cell subsets are present in individuals with a history of cutaneous leishmaniasis, further studies are needed to characterize CD4+ TRM cell populations." (PMID 38469319, 2024). "In cutaneous leishmaniasis, caused by Leishmania (Viannia) braziliensis (Lb), a higher frequency of CD8 T, NK, and NKT-like cells, contrary to CD4 T cells, in cultures of PBMC collected from patients before treatment and exposed to Lb antigens was observed." (PMID 36769064, 2023). "CD8+ NKT-like cells appear to be protective in both cases of visceral or cutaneous leishmaniasis, in contrast to CD4+ NKT-like cells." (PMID 36769064, 2023). "Cutaneous leishmaniasis is a localized infection controlled by CD4+ T cells that produce IFN-γ within lesions." (PMID 33793565, 2021). "We recently demonstrated that skin-resident CD4+ T cells play a critical role in immunity to cutaneous leishmaniasis, however the various mechanisms by which CD4+ TRM cells mediate protection in the skin remain ill-defined." (PMID 28419151, 2017). "In contrast, prevention and cure of cutaneous leishmaniasis caused by L. (L.)amazonensis involved a CD8+ T-cell response to the F1 domain, besides the CD4+ T-cell response to the F3 domain." (PMID 28747911, 2017).
cutaneous leishmaniasis (continued). "Although CD4+ T cells are critical for protective immunity in cutaneous leishmaniasis, CD8+ T cells have also been shown to be essential in certain situations, particularly in low dose infections." (PMID 25412267, 2014). "The capacity of B cells specific for Leishmania antigens in peripheral blood of cutaneous leishmaniasis patients to activate CD4 T cells and induce cytokine secretion is similar to that of all cell populations present in PBMCs." (PMID 24568275, 2014). "CD4 T cell activation by B cells of cutaneous leishmaniasis patients was evaluated by culture of PBMCs or purified B cells and CD4 T cells with Leishmania panamensis antigens." (PMID 24568275, 2014). "Our group reported that CD4+CD25+ T cells present in skin lesions of patients with cutaneous leishmaniasis display phenotypic and functional characteristics of natural Treg cells." (PMID 23656976, 2013). "Previous studies revealed that protection against L. major infection in mice and healing of cutaneous leishmaniasis in humans correlates with the priming of multifunctional Th1 CD4+ T cells that simultaneously secrete high amounts of IFN-γ, IL-2, and TNF-α." (PMID 23840706, 2013). "Cutaneous leishmaniasis results in an adaptive Th1 CD4+ T cell response that efficiently clears the parasite, but may also result in scaring." (PMID 27009263, 2016). "Experimental cutaneous leishmaniasis in genetically inbred mice was the first model which showed a mouse strain-dependent polarization of IL-4 and IFN-γ production by CD4+ T cells correlating with either disease susceptibility or resistance and therefore formed the basis of the Th1 and Th2 paradigm." (PMID 26834705, 2015). "The capacity of B cells to activate CD4 T cells in human cutaneous leishmaniasis caused by Leishmania (Viannia) has not been evaluated." (PMID 24568275, 2014). "The results suggested that immune response in protected individuals with a history of zoonotic cutaneous leishmaniasis (ZCL) due to L. major is mediated not only through the expansion of antigen-specific IFN-γ producing CD4+ Th1 cells, but also through IFN-γ producing CD8+ T cells." (PMID 20967288, 2010). "This study provides novel insights into the immunopathogenesis of human cutaneous leishmaniasis (CL), demonstrating that Leishmania (Viannia) braziliensis distinctly modulates the release of extracellular vesicles (EV), including those derived from CD4+, CD8+, and CD14+ immune cells." (PMID 40872281, 2025). "Tissue-resident memory CD4+ T cells provide protection after a parasite challenge and this requires the recruitment and activation of inflammatory monocytes by producing reactive oxygen species and NO, which plays a critical role in immunity to cutaneous leishmaniasis." (PMID 39201440, 2024). "Thus, while the role of this subset in mediating the immunopathogenesis of cutaneous leishmaniasis (CL) is evident, it remains unclear whether CD4+ cells acquire cytotoxic capacity and if they may also contribute to exacerbating the severity of skin lesions." (PMID 39497830, 2024). "In mice vaccinated with NH36, protection against VL is mediated by a CD4+ T cell response to the NH36 C-terminal domain (F3), and against cutaneous leishmaniasis (CL), by a CD4+ response against F3 and a CD8+ response against the NH36 N-terminal (F1)." (PMID 40666521, 2025). "Although multiple factors influence resistance to cutaneous leishmaniasis, the induction of IFN-γ producing CD4+ T cells (Th1 cells) is the critical component that ensures effective parasite killing in infected macrophages." (PMID 40096189, 2025). "The authors analyzed cellular infiltration and immunohistochemistry staining for CD4, CD8 and IL-17 in biopsy samples from 33 patients with cutaneous leishmaniasis before treatment." (PMID 34330599, 2021).
cutaneous leishmaniasis (continued). "In murine cutaneous leishmaniasis (CL), particularly in L. amazonensis infection, the blockade of PD-1 and PD-L1 reduced parasite load, and also increased IFN-γ-producing CD4+ and CD8+ T cells." (PMID 34281214, 2021). "To do this we correlated the EMRA CD4+ and CD8+ T cell subsets with the size of the skin lesions in patients with cutaneous leishmaniasis." (PMID 30662437, 2018). "Leishmania reactive CD4+ and CD8+ T cells are expanded in long-term healed cutaneous leishmaniasis (hCL) patients but their functional characteristics remain to be determined." (PMID 24303052, 2013). "Moreover, indicating an exhaustion process, anti-PD-L1/PD-L2 added to cultures of CD4+ and CD8+ T cells from cutaneous leishmaniasis patients increased the response to L. braziliensis antigen, and restored their IFN-γ response." (PMID 34211455, 2021). "In addition, we recently observed that the predicted epitopes for CD8+ T cells of F1 induced in vitro stimulating activity on both the CD4+ and the CD8+ T-cell populations in mice vaccinated against cutaneous leishmaniasis." (PMID 28747911, 2017). "A recent study has shown that individuals cured of cutaneous leishmaniasis presented a significant increase in CD4+ and CD8+ TEM without IFN-γ production in response to the L. brasiliensis antigen." (PMID 25992795, 2015). "The clinical manifestations of cutaneous leishmaniasis and mucocutaneous leishmaniasis may differ in HIV infection with the degree of reduction in CD4 count as an important factor." (PMID 25412435, 2014). "Culture of PBMCs from cutaneous leishmaniasis patients with Leishmania antigens resulted in upregulation of the activation markers CD25 and CD69 as well as increased frequency of CD25hiCD127- cells among CD4 T cells." (PMID 24568275, 2014). "In murine models, IFNγ- and IL-10-producing CD4+ T cells emerge during experimental infection with Toxoplasma gondii and in non-healing cutaneous leishmaniasis, where they were shown to protect mice against immune-related pathology at the cost of pathogen persistence." (PMID 41000872, 2025). "In human cutaneous leishmaniasis, IFN-γ production is one of the indicators of a sustained cell-mediated immune response, which is mediated not only through expansion of antigen-specific IFN-γ-producing CD4+ Th1 cells, but also through IFN-γ-producing CD8+ T cells." (PMID 22911786, 2012). "However, in cutaneous leishmaniasis, anti-PD-L1 treatment, but not anti-PD-L2, significantly increased IFN-γ-producing CD4+ and CD8+ T cells, with significantly lower parasite loads but bigger lesions." (PMID 36668953, 2023). "Taken together, the data obtained in this study suggest that CD4+ T lymphocytes and FoxP3+ T regulatory cells, as well as TGF-β+ and IL-10+ cells, although discrete, play an important role in the immunopathogenesis of nonulcerated or atypical cutaneous leishmaniasis." (PMID 29743809, 2018).